NCOA4 (nuclear receptor coactivator 4)
Description:
Cargo receptor for the autophagic turnover of the iron-binding ferritin complex, playing a central role in iron homeostasis. Acts as an adapter for delivery of ferritin to lysosomes and autophagic degradation of ferritin, a process named ferritinophagy. Targets the iron-binding ferritin complex to autolysosomes following starvation or iron depletion. Ensures efficient erythropoiesis, possibly by regulating hemin-induced erythroid differentiation. In some studies, has been shown to enhance the androgen receptor AR transcriptional activity as well as acting as ligand-independent coactivator of the peroxisome proliferator-activated receptor (PPAR) gamma. Another study shows only weak behavior as a coactivator for the androgen receptor and no alteration of the ligand responsiveness of the AR. Binds to DNA replication origins, binding is not restricted to sites of active transcription and may likely be independent from the nuclear receptor transcriptional coactivator function. May inhibit activation of DNA replication origins, possibly by obstructing DNA unwinding via interaction with the MCM2-7 complex.
Synonyms: ARA70; ELE1; RFG; PTC3; DKFZp762E1112
Tractability: Small molecule: a structure with a bound ligand is known. PROTAC: UniProt records ubiquitination sites on it; ubiquitination databases record sites on it; a small molecule that binds it is known.
Gene: Protein-coding gene on chromosome 10 (46,005,085 to 46,030,669, reverse strand). Ensembl gene ENSG00000266412.
Subcellular location: Cytoplasmic vesicle, autophagosome; Autolysosome; Nucleus; Chromosome
Subcellular location (Human Protein Atlas): Nucleoli; Cytosol; Golgi apparatus
Gene Ontology:
Molecular function: protein binding; transcription coactivator activity
Biological process: protein targeting to lysosome; autophagy; cellular response to estrogen stimulus; cellular response to testosterone stimulus; erythrocyte differentiation; estrogen receptor signaling pathway; intracellular iron ion homeostasis; male gonad development; response to hormone; positive regulation of DNA-templated transcription
Cellular component: autolysosome; chromosome; nucleus; autophagosome
Genetic constraint (gnomAD): Loss-of-function variants: 30 observed, 62.6 expected, observed/expected ratio (o/e) 0.48, 90% interval 0.36 to 0.65. The upper end of that interval is the gene's LOEUF score, 0.65, which puts it in group 2 of 6, group 1 being the genes least tolerant of losing a copy. Missense variants: 572 observed, 690.34 expected, observed/expected ratio (o/e) 0.83, 90% interval 0.77 to 0.89. Synonymous variants: 217 observed, 239.24 expected, observed/expected ratio (o/e) 0.91, 90% interval 0.81 to 1.01.
Homologues: Orthologues: chimpanzee NCOA4 (99% identical), pig NCOA4 (87% identical), macaque NCOA4 (86% identical), dog NCOA4 (84% identical), mouse Ncoa4 (81% identical), rat Ncoa4 (78% identical), guinea pig NCOA4 (78% identical), zebrafish ncoa4 (37% identical).
Diseases named in the same sentence as NCOA4 in open-access papers:
NCOA4 is named in the same sentence as 171 diseases in open-access papers, as found by Europe PMC text mining. Sharing a sentence is not in itself a finding about the gene and the disease. The quoted sentences say what the papers report.
papillary thyroid carcinoma (42 papers, 1998 to 2025). "NCOA4 was initially identified in papillary thyroid carcinoma and is also referred to as androgen receptor-associated protein 70 (ARA70)." (PMID 40794264, 2025). "Among the gene fusion patients, two cases of NCOA4-RET fusion were of the Diffuse Sclerosing Variant of Papillary Thyroid Carcinoma (DSVPTC)." (PMID 38607456, 2024). "Chromosomal translocations between NCOA4 and the ret tyrosine kinase gene are associated with papillary thyroid carcinoma." (PMID 34863158, 2021). "Nuclear receptor coactivator 4 (NcoA4), also known as androgen receptor-associated protein 70 (ARA70), was initially discovered as a component of Ret-Fused Gene expressed in a subset of papillary thyroid carcinomas." (PMID 22562579, 2012). "The most frequent driver mutation in both radiation-induced and sporadic papillary thyroid carcinoma comes from the genome rearrangements between the RET gene and the PTC genes (CCDC6 and NCOA4), located close to each other on chromosome 10." (PMID 40362680, 2025). "In our recent study, we identified a novel cancer in-frame fusion transcript with the kinase domain on the 3′ end, with NCOA4-RET in an FFPE papillary thyroid cancer sample." (PMID 36009413, 2022). "Analyses in larger cohorts are warranted to clarify the precise prevalence and characteristics of thyroid papillary carcinomas that present with NCOA4-RET (RET/PTC3)." (PMID 29088743, 2017). "On the other hand, the incidence of NCOA4-RET in thyroid papillary carcinomas varies (1–86.7%) among reports." (PMID 29088743, 2017). "NcoA4 was initially discovered as a component of Ret Fused Gene (RFG), a novel fusion protein expressed in papillary thyroid carcinoma, that combines the N-terminal region of NcoA4 with the constitutively active tyrosine kinase domain of the ret oncogene." (PMID 22562579, 2012). "The involvement of NcoA4 as part of the RET/PTC3 fusion protein in papillary thyroid carcinomas (PTCs) has been studied extensively." (PMID 22562579, 2012). "For instance, CDCC6 and NCOA4 are commonly found in papillary thyroid cancer." (PMID 39518080, 2024). "Thus, this study aimed to determine the prevalence of CCDC6::RET and NCOA4::RET fusions in Thai papillary thyroid carcinoma patients." (PMID 37188126, 2023). "Nuclear receptor coactivator 4 (NCOA4), also known as androgen receptor-associated protein 70 (ARA70), was originally discovered to be a component of the RET-fused gene expressed in a subset of papillary thyroid carcinomas." (PMID 35756082, 2022). "In approximately 20% of human papillary thyroid carcinoma (PTC), RET exons encoding the tyrosine kinase domain are fused to the promoter region and the 5’-ter exons of heterologous genes, generating chimeric oncogenes, such as CCDC6-RET (RET/PTC1) or NCOA4-RET (RET/PTC3)." (PMID 26046350, 2015). "Of note, the most common fusion in papillary thyroid carcinoma was CCDC6-RET and NCOA4-RET (41.3% and 35.8%, respectively)." (PMID 36690680, 2023). "NCOA4, also named as ARA70, was described at first being a composition of RetFused Gene expressed in an experimental cohort of papillary thyroid carcinomas." (PMID 34681938, 2021). "Three cases were characterized by NCOA4-RET, CCDC6-RET, and SND1-BRAF fusions, which are more commonly seen in papillary thyroid carcinoma." (PMID 33441414, 2021). "RET fusions have been described in up to one-third of papillary thyroid cancers and in 2% of lung adenocarcinoma cases; CCDC6-RET and NCOA4-RET are the most commonly identified RET fusions." (PMID 32411236, 2020). "The NCOA4-RET fusion gene is detectable in several types of cancer, including thyroid papillary carcinoma, NSCLC, colon cancer, and salivary gland duct cancer." (PMID 29088743, 2017). "The mesothelioma cell line EHMES-10 containing a NCOA4-RET fusion, and human lung adenocarcinoma cell line LC-2/ad and thyroid papillary carcinoma cell line TPC-1 containing a CCDC6-RET fusion were used in this study." (PMID 29088743, 2017).
papillary thyroid carcinoma (continued). "RET fusions (involving CCDC6, PRKAR1A, NCOA4 (ELE1), GOLGA5, TRIM24 (HTIF1), TRIM33 (RFG7), and KTN1 and ERC1 (ELKS)) are found in papillary thyroid cancers." (PMID 22928112, 2012).
thyroid cancer (30 papers, 2003 to 2025). "Analyzed RET/PTC1 and RET/PTC3 are intrachromosomal inversions involving the RET and CCDC6 or NCOA4 genes, respectively, which are prevalent in thyroid cancers in individuals exposed to radiation after the Chernobyl nuclear accident." (PMID 29568381, 2018). "The frequency of CCDC6::RET in sporadic thyroid cancer is higher than that of NCOA4::RET." (PMID 37188126, 2023). "In cases of thyroid cancer, the predominant fusion events involve RET/PTC1 and RET/PTC3, which entail the fusion of the RET gene with the CCDC6 gene and the NCOA4 gene, respectively." (PMID 40586006, 2025). "The most common RET fusions in PTC are CCDC6-RET (RET/PTC1) and NCOA4-RET (RET/PTC3), found in 90% of fusion-positive cases, whereas other follicular-derived thyroid cancers rarely harbour RET fusions." (PMID 40332222, 2025). "The RET/PTC1 (CCDC6-RET) is the most common rearrangement, accounting for 60% of thyroid cancer with RET rearrangements, followed by RET/PTC3 (NCOA4-RET, 30%), and RET/PTC2 (PRKAR1A-RET, 5%)." (PMID 31835496, 2019). "In contrast to 13 fusion partner genes of RET in thyroid carcinoma, only KIF5B-RET, CCDC6-RET, TRIM33-RET and NCOA4-RET have been reported in lung cancer, and KIF5B-RET is the most commonly identified gene fusion in NSCLCs to date." (PMID 25047660, 2014). "Previously reported fusion genes in thyroid cancer, ETV6–NTRK3 (4.80% in PTC), CCDC6–RET (2.40% in PTC), NCOA4–RET (0.80% in PTC), SQSTM1–NTRK1 (0.80% in PTC), STRN–ALK (0.80% in PTC), and PAX8–PPARG (0.80% and 1.82% in PTC and FTN, respectively), were also identified." (PMID 27494611, 2016).
prostate carcinoma (23 papers, 2010 to 2025). A carcinoma that arises from epithelial cells of the prostate gland. "SNP rs10993994 (near NCOA4) is associated with prostate cancer, and the risk allele is associated with increased expression of five NCOA4 isoforms in histologically normal prostate tissue." (PMID 31323811, 2019). "Single nucleotide polymorphisms (SNP) in chromosome 10q11 have been associated with prostate cancer, with some of these SNPs localizing to NcoA4." (PMID 22562579, 2012). "Because regulatory elements can interact with many genes, and since both MSMB and NCOA4 are strong candidates for prostate cancer risk, we evaluated the relationship between risk allele status and transcript abundance of these genes across both normal and tumor prostate tissues." (PMID 21085629, 2010). "If an association between genotype and expression of MSMB or NCOA4 were observed in tissue other than prostate, then that gene may be less likely to be involved in prostate cancer risk." (PMID 21085629, 2010). "High NCOA4 expression inhibits the proliferation of prostate cancer cells and promotes the proliferation and invasion of breast cancer cells." (PMID 40788949, 2025). "In contrast, another study demonstrated higher NCOA4 expression in prostate cancer tissues than benign tissue." (PMID 31323811, 2019). "When compared to normal prostate tissues (N = 52), the CTBP2 expression level was significantly higher in prostate cancer tissues (N = 498) (p = 0.0185), while the NCOA4 expression was significantly lower in prostate cancer tissues (p = 0.0131)." (PMID 31323811, 2019). "Two well-studied NCOA4 isoforms (NCOA4α and NCOA4β) have been functionally assessed in breast and prostate cancers." (PMID 29435183, 2018). "There exists two well-studied NCOA4 isoforms (NCOA4α and NCOA4β) with opposing functions in breast and prostate cancers." (PMID 29435183, 2018). "This is in contrast to the NCOA4 localization in prostate cancer specimens in which the NCOA4α isoform is localized to the cytoplasmic compartment and the NCOA4β isoform is localized in the nuclear compartment." (PMID 29435183, 2018). "Despite the fact that both NcoA4α and β function as AR coactivators in cell-based reporter assays, full-length NcoA4 suppressed androgen-induced proliferation of AR-expressing prostate cancer cell lines in vitro and in vivo." (PMID 22562579, 2012). "NcoA4 mRNA and protein expression has been demonstrated in secondary prostate cancer cell lines, LNCaP, PC-3, and DU145." (PMID 22562579, 2012). "For example, gene BRCA1 with degree 129 is strongly related to prostate cancer, and articulation hub of gene NCOA4 with only degree 8 is also the annotated cancer gene in prostate cancer." (PMID 22577352, 2012). "Altogether, these studies indicate the need for further investigations to clarify the expression and/or distribution of NcoA4 isoforms in prostate cancer." (PMID 22562579, 2012). "Altered expression of NcoA4 has also been reported in several cancers with expression of isoforms reported for both breast and prostate cancer." (PMID 21814571, 2011). "While a role of NcoA4 in proliferation has been described in prostate cancer cell lines, these effects are dependent upon androgen and are likely due to NcoA4 functioning as an AR coregulatory protein." (PMID 21814571, 2011). "Genetic data presented here demonstrate that the chromosome 10q11 prostate cancer risk locus is associated with decreased levels of MSMB and increased levels of NCOA4 RNA expression." (PMID 21085629, 2010). "Intriguingly, although authors previously reported a tumor-suppressor function of full-length NCOA4, in contrast, an AR-dependent promotion of NCOA4b was shown in prostate cancer cell growth and invasion, suggesting a role of full-length NCOA4 in regulating normal cell proliferation." (PMID 38961066, 2024).
prostate carcinoma (continued). "NCOA4 was originally described as a coactivator of multiple nuclear hormone receptors, and is closely related to the tumorigenesis and progression in ovarian cancer, prostate cancer, breast cancer and pancreatic cancer." (PMID 36552889, 2022). "Clearly, the role of NCOA4 in prostate cancer needs further exploration." (PMID 31323811, 2019). "However, another study showed similar expression levels of NCOA4 in both normal and prostate cancer." (PMID 31323811, 2019). "Several studies indicate that NcoA4 localizes predominantly to the cytoplasm and affects ligand-binding specificity of the androgen receptor, which has important implications for androgen-independent prostate cancer." (PMID 22562579, 2012). "In addition to ligand specificity, NcoA4 overexpression reverses the antagonistic activity of hydroxyflutamide, an AR antagonist widely used in the treatment of prostate cancer." (PMID 22562579, 2012). "This window lies not in MSMB but in a neighboring gene, NCOA4, also a candidate gene for prostate cancer risk." (PMID 20976246, 2010). "Other reported functions for NCOA4 include (a) regulation of DNA replication to modulate DNA stability, (b) modulation of DNA damage response and cellular senescence, and (c) increasing cellular proliferation and migration/invasion of breast as well as prostate cancer cells." (PMID 29435183, 2018). "Overexpression of NcoA4 has been shown to enhance AR transactivation induced by ligands other than active androgens, which may have negative implications for the success of hormonal therapies used in the treatment of prostate cancer." (PMID 22562579, 2012). "A read-through fusion transcript of NCOA4 and MSMB has recently been demonstrated in some prostate cancers." (PMID 26939004, 2016). "However, altered expression of NcoA4 in human prostate cancer has not been firmly established." (PMID 22562579, 2012).
breast cancer (22 papers, 2010 to 2025). A primary or metastatic malignant neoplasm involving the breast. "Conversely, the reduction of the NCOA4 full-length isoform in MCF-7 cells was associated with increased breast cancer metastasis, while NCOA4 knockdown in MCF-7 cells led to reduced cell proliferation." (PMID 35311114, 2022). "Included among these are Sirt1, Hey2, Ncoa4, and Foxa1, all of which have been implicated in the progression of luminal breast cancer and ER-α-dependent signaling, as well as ER-α (that is, Esr 1)." (PMID 20565980, 2010). "In MCF7 breast cancer cells, NCOA4 was associated with proliferation and invasion." (PMID 34741349, 2021). "Limited preclinical evidence has been generated in BC models harboring RET rearrangements with the available evidence indicating that cabozantinib reduces the proliferative potential of breast cancer cells displaying the NCOA4-RET fusion." (PMID 39211557, 2024). "Further analysis of the CPTAC dataset revealed that overall NCOA4 protein expression was significantly greater in breast cancer (p < 0.001), clear cell renal cell cancer (p < 0.001), and UCEC (p < 0.001)." (PMID 35756082, 2022). "Several studies have investigated the role of steroid hormone receptor coactivators in breast cancer and are suggestive of a role for NcoA4." (PMID 22562579, 2012). "Increased NcoA4 expression was observed in breast cancer cell lines undergoing EMT induced by co-culture with bone marrow-derived mesenchymal stem cells (MSCs)." (PMID 22562579, 2012). "NcoA4 expression has been demonstrated in multiple human breast cancer cell lines with some of these cells expressing NcoA4β." (PMID 22562579, 2012). "High levels of NcoA4 protein have been shown in human benign breast epithelium and in situ breast carcinomas." (PMID 22562579, 2012). "Recent studies have shown that tetrandrine citrate can inhibit breast cancer by activating NCOA4." (PMID 39844412, 2025). "Notably, TetC‐induced ferritin cell death demonstrated inhibition of GPX4 expression and activation of NCOA4‐mediated ferritin phagocytosis in breast cancer cells." (PMID 38140764, 2024). "When breast cancer cells were directly co-cultured with MSCs, they demonstrated substantial overexpression of oncogenes (NCOA4, FOS), proto-oncogenes (FYN, JUN), and EMT specific markers, as well as shape and growth pattern changes, resulting in breast cancer metastasis." (PMID 34736460, 2021). "However, addition of a RET inhibitor to treatment of an ER+/HER2 treatment-refractory, NCOA4-RET- positive breast cancer resulted in a clinical response." (PMID 30446652, 2018). "For the NCOA4-RET fusion-positive, ER+/ERBB2-amplified breast cancer, one can speculate that the presence of NCOA4-RET contributed to its relative resistance to primary treatment with aromatase inhibitor, trastuzumab, and pertuzumab." (PMID 30446652, 2018). "Interestingly, AR signaling in ER+ breast cancer is thought to be associated with favorable prognosis, and the reduction of HIPK3 and NCOA4 may negatively affect AR signaling and ER+ breast cancer prognosis." (PMID 35311114, 2022). "This study suggests that NcoA4 may reflect or promote breast cancer metastasis." (PMID 22562579, 2012). "The co-localization of NcoA4 with α-tubulin was observed with T47D human breast cancer cells, and African green monkey kidney cells (COS) and human ovarian cancer cells (ES2), indicating that the association of NcoA4 with microtubules during mitosis occurs in different mammalian cell types." (PMID 21814571, 2011). "Activates NCOA4-mediated ferritinophagy and JNK signaling to trigger ferroptosis; the mechanism is informative for breast cancer translation." (PMID 41008615, 2025). "LA dose-dependently decreased breast cancer cell survival and impaired mitochondrial structure and function, possibly through suppressing the expression of GXP4 and downregulating nuclear receptor coactivator 4 (NCOA4)." (PMID 36355532, 2022).